CDH13 (cadherin 13)
Diseases named in the same sentence as CDH13 in open-access papers (continued):
Sharing a sentence is not in itself a finding about the gene and the disease.
ovarian dysfunction (1 paper, 2025). The inability of the ovaries to function. "Notably, intersection of the DEG datasets across all timepoints revealed two consistently altered genes, Cdh13 and Slc2a1, highlighting them as potential key mediators of IVF-associated ovarian dysfunction and accelerated reproductive aging." (PMID 41278955, 2025).
ovarian tumors (1 paper, 2025). "Clinically, CDH13 promoters are more heavily methylated in ovarian tumors than in normal tissue, and a DNA-methyltransferase inhibitor can reactivate CDH13 expression in cancer cells and its anti-tumor functions." (PMID 40649905, 2025).
personality disorder (1 paper, 2021). A diverse category of psychiatric disorders characterized by behavior that deviates markedly from the expectations of the individual's culture; this pattern of deviation is pervasive and inflexible and is stable over time. "The association of CDH13 with agreeableness and extraversion, and the frequent comorbidity of ADHD with personality disorders gave reason to investigate the association of rs2199430 with the Big Five personality traits." (PMID 34573337, 2021).
prostate tumor (1 paper, 2021). "The expression of CDH13 has been associated with poor PCa prognosis and low proliferation rates of prostate tumor cells." (PMID 33927218, 2021).
psoriasis vulgaris (1 paper, 2017). Plaque psoriasis is the most common presentation of psoriasis. "Cdh13 expression is also observed to be significantly reduced in both invasive cutaneous SCC and psoriasis vulgaris lesions and is thus considered to be an endogenous negative regulator of keratinocyte proliferation and also a crucial preserver of healthy skin architecture." (PMID 28587635, 2017).
psychosis (1 paper, 2021). "Besides, our results confirm previous results suggesting the involvement of MACF1, CNTN6, and CDH13 in the etiology of psychosis." (PMID 33897758, 2021). "More research is needed to further elucidate the role of MACF1 in psychosis as well as its interaction with CNTN6 and CDH13." (PMID 33897758, 2021).
rectal adenocarcinoma (1 paper, 2015). "Finally, a key feature of the primary rectal adenocarcinoma was APC and CDH13 methylation, suggesting an aberrant activation of the wingless signaling pathway that is considered a nearly ubiquitous event in CRC." (PMID 26231173, 2015).
renal carcinoma (1 paper, 2021). A carcinoma arising from the epithelium of the renal parenchyma or the renal pelvis. "However, the regulatory mechanism of CDH13 on renal cancer angiogenesis remains to be further studied." (PMID 33761933, 2021).
retinal disease (1 paper, 2021). "Given the potential role of small vessel plasticity in the pathogenesis of retinal disease in T2D patients, our findings support the hypothesis that CDH13, and in general the CDH superfamily may play a role in eye pathologies in T2D." (PMID 33531528, 2021).
seminoma (1 paper, 2014). A radiosensitive malignant germ cell tumor found in the testis (especially undescended), and extragonadal sites (anterior mediastinum and pineal gland). "But H-cadherin (CDH13), one of the predicted gene targets of miR-2184 reported in TargetScanFish, has been shown to be downregulated in testicular germ cell tumors and associated with differentiation of seminoma." (PMID 25350659, 2014).
serous ovarian carcinoma (1 paper, 2023). "In addition, the same group recently investigated PCDH17 gene methylation (with other genes namely CDH13, HNF1B and GATA4) in high grade serous ovarian carcinoma." (PMID 36698136, 2023).
substance dependence (1 paper, 2011). The psychological or physiological need to take a substance in order to experience its effects or to avoid the effects of its absence. "We initially identified associations between substance dependence vulnerability and CDH13 variants in smaller subsets of COGA and MNB samples in studies that utilized earlier microarray types." (PMID 21818250, 2011).
tumor (114 papers, 2004 to 2026). "In different cancer entities (e.g., lung, ovarian, esophageal, bladder, cervical, prostate), CDH13 was already suggested to be a tumor-suppressive factor, and its downregulation was associated with tumor growth and metastasis." (PMID 38791932, 2024). "LANA cooperates with DNMT3a and facilitates promoter methylation of cadherin 13 to cause its downregulation in various tumors, leading to cell proliferation, tumor invasion, and suppression of apoptosis." (PMID 35008848, 2021). "BIRC5/Survivin is known as an apoptosis inhibitor, while Serbp1/Serpine-1/PAI-1 is associated with tumor invasion, and MIG6 and Cadherin 13 are known as tumor suppressors." (PMID 34371830, 2021). "On the other hand, re-expression of CDH13 in most tumor cell lines inhibits tumor growth through enhanced susceptibility to apoptosis and subdued carcinogenic processes, including invasiveness, proliferation, and angiogenesis." (PMID 33407434, 2021). "HER2 amplification in DCIS tumours was associated with methylation of CDH13 (P = 0.009), and RARβ (P = 0.042)." (PMID 25331261, 2014). "This pattern of expression corroborates current literature, suggesting a possible role for CDH13 expression in tumor-associated vasculogenesis." (PMID 24979721, 2014). "CDH13 appears to be frequently methylated in cancer, however its expression has been reported to be upregulated in tumor-associated vasculature, where it promotes endothelial cell proliferation and migration." (PMID 24979721, 2014). "In addition, hypermethylated CDH13 results in the loss of its expression, which is related to metastasis, invasiveness, and tumor malignancy." (PMID 37901797, 2023). "In addition, tumours with organ secondaries were associated with less methylation of cadherin 13 gene, CDH13, and CXCL12." (PMID 25052224, 2014). "These analyses identified several differentially methylated genes linked to invasiveness (e.g., PHYHD1, WNT4, STAT6, CDH1, CDH13), aggressive behaviour (e.g., AIP, PDCD1, LINE-1), and tumour regrowth (e.g., TERT, FAM90A1, ING2)." (PMID 41866138, 2026). "CDH13 often restrains cancer cell proliferation, invasion, and overall tumor growth, yet paradoxically supports tumor progression by promoting neovascularization." (PMID 40649905, 2025). "In bladder cancer, tumor-suppressor genes such as RASSF1A, RUNX3, CDH13, and HOXA9 have been reported to undergo promoter hypermethylation, resulting in loss of tumor-inhibitory function." (PMID 41377897, 2025). "Epigenetic control emerges to play an important role in CDH13 regulation: hypermethylation of the CDH13 promoter correlated with CDH13 silencing and oncogenic transformation across many tumor types." (PMID 40649905, 2025). "CDH13 expression in many tumor cell lines inhibits cell proliferation and invasiveness, increases susceptibility to apoptosis, and reduces tumor growth in vivo models." (PMID 39781343, 2025). "Elevated DNMT1 then hypermethylates CpG-rich promoters of the key tumor suppressors, including CDH13, hampering their transcription and disrupting cell–cell adhesion across multiple malignancies (lung, gastric, and breast)." (PMID 40649905, 2025). "These associations were particularly strong for cell cycle-/apoptosis-related genes (RUNX3, RASSF1A, and CDH13), suggesting that epigenetic silencing of key regulatory checkpoints facilitates early tumor recurrence and progression." (PMID 41377897, 2025). "The consequent rise in DNMT1 hypermethylates the CpG-rich CDH13 promoter, thus blocking T-cadherin tumor-suppressive activity." (PMID 40649905, 2025). "CDH13 (also known as H-cadherin and T-cadherin) is a member of the cadherin gene class mapped to 16q24, acts as a tumor suppressor gene, and its downregulation has been reported in many cancer types, while being associated with poor prognosis." (PMID 41373857, 2025). "CDH13 expression is physiologically atypical, and reexpression is observed in various tumor diseases, including even in ccRCC." (PMID 40699665, 2025).
tumor (continued). "Although none of the cited studies directly explored a connection between hsa-miR-199b and CDH13 expression, T-cadherin itself is widely viewed as a tumor suppressor in numerous malignancies." (PMID 40649905, 2025). "K562, KCL22, KU812, and NB4 had lower expression of CDH13 mRNA than other tumor cell lines of the hematological system, and were selected for subsequent experiments." (PMID 39179585, 2024). "Treatment with 5′-aza-2-deoxycytidine (decitabine) restored the expression of the CDH13 gene and inhibited tumor growth." (PMID 39179585, 2024). "The regulation of tumor-related integrin function, gene transcription, metabolism, and amide and phospholipid metabolism are the main functions of CDH13 and its ANGs." (PMID 39545598, 2024). "CDH13 serves as an important tumor suppressor responsible for cell–cell adhesion, often deactivated by abnormal promoter hypermethylation during carcinogenesis." (PMID 38926485, 2024). "This leads to the re-expression of methylation-silenced tumor-suppressor genes, such as fragile histidine triad protein (FHIT), CDKN2A, cadherin-13 (CDH13), cadherin-1 (CDH1) and Ras Association Domain Family Member (RASSF1A) both in vitro and in vivo." (PMID 37047090, 2023). "The CDH13 promoter methylation status in NSCLC tumor tissue and NSCLC plasma samples was identified." (PMID 37901797, 2023). "Another down-regulated gene cadherin-13 (CDH13) in obese and lean cohorts, also called H-cadherin or T-cadherin, belongs to the cadherin superfamily and is a cell adhesion molecule and functions as a tumour suppressor gene." (PMID 36232772, 2022). "In previous studies, CDH1 and CDH13 were proved as functional tumor inhibitory factors, involved in inhibiting the invasion, proliferation and metastasis of tumor cells." (PMID 33442417, 2021). "CDH13, also known as T cadherin, is frequently silenced in many different cancers and considered as a tumor suppressor genes." (PMID 33761933, 2021). "DMA identified 59,654 differential methylation sites between two clusters and part of these sites were correlated with tumor angiogenesis genes including CDH13, COL4A3, and RHOB." (PMID 33761933, 2021). "The expression of the MIG6 (>two-fold) and Cadherin 13 (three-fold) genes were up-regulated (p < 0.05) in tumor tissue from γT3-fed mice." (PMID 34371830, 2021). "Cadherin 13 is frequently silenced in different cancers, and it has long been considered a tumor suppressor." (PMID 34371830, 2021). "The overexpression of CDH13 effectively inhibited the proliferation and invasion of tumor cells derived from glioma, cutaneous squamous cell carcinoma and oral squamous cell carcinoma 13-15." (PMID 32127937, 2020). "Researchers found that higher methylation values of four genes (RASSF1A, CDH1, CDH13, and APC) were significantly associated with several traits of poorer outcome (tumor stage, growth pattern, muscle invasion, and tumor grade)." (PMID 33092083, 2020). "Cadherin 13 (CDH13) is an atypical cadherin that exerts tumor-suppressive effects on cancers derived from epithelial cells." (PMID 32127937, 2020). "To clarify the in vivo role of CDH13, we further performed studies in orthotopic tumor and subcutaneous tumor mouse models." (PMID 32127937, 2020). "The methylation rate of CDH13 gene was relatively lower in non-tumor control samples, with a mean methylation frequency of 1.1 % in this study." (PMID 27578166, 2016). "The expression of CDH13 in human tumor cells can inhibit their invasive potential and markedly reduce their proliferation." (PMID 27578166, 2016). "The analyses of CDH13 methylation and gender, tumor grade and tumor number used the random effects model, while a fixed effects model was used for tumor stage." (PMID 27578166, 2016). "CDH13 is a cell adhesion protein and decreased expression of this gene plays an essential role in tumor metastasis." (PMID 27065772, 2016).
tumor (continued). "For LVI, the model identified seven CpGs from three genes as the most informative variables: CDH1 (sites 1, 2 and 4), CDH13 (sites 2 and 5) and methylated-in-tumour 3, MINT3 (sites 6 and 9)." (PMID 25052224, 2014). "CDH13 presents as a potential novel anti-angiogenic target in ccRCC, and further investigation of its specific role in tumor vasculogenesis is warranted." (PMID 24979721, 2014). "CDH13 expression appears to be significantly upregulated in RCC tumor vasculature at all stages of disease as compared to normal samples." (PMID 24979721, 2014). "Our results also confirm that overexpression of CDH13 protein appears to be exclusive to tumor vasculature." (PMID 24979721, 2014). "Of these, we further establish a role for CDH13 in tumor angiogenesis, as well as a pro-migratory role for four novel factors including KISS1R, KSR1, CAMK1, and SSPN in ccRCC." (PMID 24979721, 2014). "Tumor size was associated with RIL and CDH13 methylation (both p = 0.002), and S-phase was associated with RIL methylation (p = 0.036)." (PMID 22695491, 2012). "The CDH13 gene is a well-known tumor suppressor gene whose protein product is a putative mediator of cell-cell interaction and cancer cell invasion and metastasis." (PMID 22701537, 2012). "CDH13, or H-cadherin, is a cell adhesion molecule with tumor-suppressor properties and an established correlation between methylation and expression." (PMID 21760961, 2011). "Therapeutically, by antagonizing miR-142-3p, or pharmacologically, by suppressing DNMT1, could restore CDH13 expression and inhibit tumor progression." (PMID 40649905, 2025). "Cadherin-13 (CDH13) plays a regulatory role in tumor growth and promotes angiogenesis." (PMID 36718454, 2023). "Previously, the frequency of methylated CDH13 was detected in 66% of the tumor samples." (PMID 37901797, 2023). "Cadherin 13 inhibits cell proliferation and tumor invasion and increases apoptosis." (PMID 35008848, 2021). "In this study, γT3 significantly (p < 0.05) up-regulated the expression of Cadherin 13 compared to the control, which indicates that it enhanced the tumor suppressing effects and, thus, could inhibit tumor development." (PMID 34371830, 2021). "As a tumor suppressor gene, CDH13 might repress gene expression when hypermethylated, possibly triggering tumorigenesis." (PMID 33407434, 2021). "In addition, treatment of cancer cell lines with a histone deacetylase inhibitor or a de-methylating agent reactivated CDH13 expression resulted in angiogenesis and tumor metastasis." (PMID 33761933, 2021). "In tumors, T-cadherin/CDH13 is often silenced in cancer cells, but up-regulated in tumor vasculature; its T-cadherin-dependent accumulation in a tumoral microenvironment may favor both neoangiogenesis and tumor growth." (PMID 32570854, 2020). "Xenograft tumor experiments were used to determine the biological function of CDH13 in vivo." (PMID 32127937, 2020). "Moreover, overexpression of CDH13 inhibited the progression of PC in vitro and in vivo, supporting its role as a tumor suppressor in PC." (PMID 32127937, 2020). "They found higher degree of methylation of MGMT, RARβ, RASSF1A, and CDH13 in tumour specimens and of SOCS-1 in peripheral blood with higher levels of IL-6, while others found less degree of methylation of USP2, TMEM49, SMAD3, DTNB, and IL-6 promoter with higher levels of IL-6." (PMID 31205673, 2019). "The aberrant methylation of CpG islands in the CDH13 promoter might lead to aberrant gene expression and further promote tumor progression." (PMID 29416663, 2018). "CDH13 re-expression can reduce tumor growth by inhibiting cell proliferation and invasiveness." (PMID 28404957, 2017). "Furthermore, CDH13 is known to function as a tumor suppressor gene, and suppression of CDH13 expression by aberrant methylation in the CpG island of its promoter has been reported in CRC and other types of cancers." (PMID 26362652, 2015).
tumor (continued). "The study found that a combination of reversion-induced LIM (RIL) and cadherin 13 (CDH13) hypermethylation was strongly correlated with ER- and PR-negative tumours, while a combination of high in normal (HIN-1) and RASSFIA methylation was associated with ER- and PR-positive tumours." (PMID 26220712, 2015). "Normal oropharynx control samples showed no promoter hypermethylation in the studied genes, except for CDH13 (40%), but the latter was still lower in control tissue (mean 13, range 7–22) compared to tumor tissue (HPV-positive: mean = 24, range 11–77; HPV-negative: mean = 20, range 6–96)." (PMID 25065733, 2014). "CDH13 underexpression was related to tumor invasion and cell migration." (PMID 24961511, 2014). "CDH13 methylation levels significantly differed by tumor size group." (PMID 22695491, 2012). "We next examined the methylation status of CDH13 promoter in tumours using the MSP technique." (PMID 14997203, 2004). "Thus, the miR-23a/27a/24-2 cluster epigenetically silences multiple tumor suppressor genes, including CDH13, establishing a feed-forward circuit accelerating NSCLC progression and offering a rationale for multi-miRNA blockade as an adjuvant strategy to prevent early relapse." (PMID 40649905, 2025). "Furthermore, increased Cdh13 expression was found to promote tumor angiogenesis in vivo." (PMID 37660920, 2023). "The 6-protein diagnostic panel consisted of FLNA, PRDX6 and ARHGDIB, associated with tumor growth, cell invasion and metastasis, GSTO1, having an antioxidant defense role (together with PRDX6), TUBA4A, found enriched in serum exosomes from NSCLC patients, and the tumor suppressor CDH13." (PMID 32575471, 2020). "CDH13 methylation may also be a prognostic biomarker for patients with tumor progression." (PMID 27578166, 2016). "Therefore, CDH13 methylation could be used as a tumour marker in clinical samples such as serum and stool for the early detection of digestive tract cancers." (PMID 15292927, 2004). "CDH13 (placental T-cadherin) on BTA18 plays a role in cell migration, brain development, and transcription repression as a tumor suppressor gene." (PMID 39766766, 2024). "In tumor and sputum samples of patients with NSCLC, aberrant promoter hypermethylation of CDH13 was detected." (PMID 37901797, 2023). "For instance, the methylation of progesterone receptor (PGR), hydroxysteroid 17-beta dehydrogenase 4 (HSD17B4), and cadherin 13 (CDH13) genes in both HER2 positive BCAFs and tumour cells was found to enhanced BC progression and invasion." (PMID 33066013, 2020). "The results showed two integration sites, one into the MICU2 and the other into CDH13 genes, the last being also found in the WES of patient’s primary tumor." (PMID 30760827, 2019). "In gene expression arrays, the overexpression of TLR4 in tumor cells correlated with gene expression of ATF-3, IL-6, CDH13, CXCL-1 and TFPI." (PMID 28982115, 2017). "An altered methylation pattern of APC, CDH13, MGMT, MLH1 and RUNX3 genes is a well recognized characteristic of CRC tumor cells." (PMID 26862732, 2016). "Among these rearrangements, 12 contained small exonal deletions, and most of the affected genes, including FHIT, CDH13, DACH1, and RBFOX1, have been reported as tumor suppressors or as deleted in cancer, suggesting their active role in tumorigenesis." (PMID 24937453, 2014). "All of these genes are known to be involved in different aspects of breast carcinogenesis, which includes tumor suppression, HIC1, CDH1, CDH13, CDKN2, DNA repair, MGMT, apoptosis, PYCARD, TNFRSF10C, and cell cycle regulation, CCNA1." (PMID 25403427, 2014). "Notable examples include E-Cadherin (CDH1), T-Cadherin (CDH13) and Proto-Cadherin 10 (PCDH10) which are recognized tumor-suppressor genes, and have been found to be hypermethylated in a number of human cancers." (PMID 23419152, 2013).